EGFR (epidermal growth factor receptor)
Diseases named in the same sentence as EGFR in open-access papers (continued):
Sharing a sentence is not in itself a finding about the gene and the disease.
cancer (continued). "Furthermore, TKI-induced EGFR dimerization is persistent in TKI-resistant cells, and inhibition of palmitoylation by 2-bromopalmitate, or targeted reduction of the kinase-inactivated EGFR by siRNA or by an EGFR-downregulating peptide, are lethal to TKI-resistant cancer cells." (PMID 31121829, 2019). "However, that is not to say that activatable fluorescence imaging could never be used for EGFR-negative cells, if another target can be found for EGFR-negative cancer." (PMID 29856819, 2018). "Although EGF–EGFR signaling is only one of several pathways involved in cancer cell proliferation and motility, the respective effects of EGF and Rab25 on integrin localization revealed in the present study may partially explain the diverse effects of EGFR-targeting drugs." (PMID 29515334, 2018). "Interestingly, melanoma cells do not express EGFR to the same extent as colorectal cancer cells, which explains in part the difference in clinical response seen from application of vemurafenib between the two cancer types." (PMID 30598662, 2018). "Thus, if a role can be ascribed to CCDC6 in the activation of the EGFR signaling, the detection of CCDC6 impairment upon TK fusion could represent an indication for targeting EGFR in cancer therapy (Cerrato A, Di Domenico I, Morra F, Celetti A, manuscript in preparation)." (PMID 29455670, 2018). "It is not clear whether the EGFR-mutant cancers have lower TMB than EGFR-wild type tumors." (PMID 30409126, 2018). "In both cancerous and non-cancerous cells, EGFR plays a crucial role in controlling key cellular pathways influencing cell proliferation, differentiation and development through MAPK and PI3K/Akt pathways and overexpression of which is associated to multiple cancer types." (PMID 30134812, 2018). "Interestingly, erlotinib-treated patients with squamous tumors tended to live longer than patients with non-squamous EGFR wild-type carcinoma, which contradicts previous findings that the prognosis of adenocarcinoma patients is generally better than that of patients with squamous tumors." (PMID 29587656, 2018). "A 2010 survey of physicians at general hospitals, chest hospitals, and comprehensive cancer centers located in 12 major cities throughout China found only 9.6% of patients with advanced NSCLC (squamous and nonsquamous histology) were tested for EGFR gene mutations." (PMID 28673332, 2017). "Interestingly, compared with wild-type PKM2, expression of R399E mutant PKM2 could more greatly enhance EGFR phosphorylation, cellular transformation and cell proliferation, which unveils a new effect of extracellular PKM2 on promoting cancer cell proliferation through EGFR activation." (PMID 29299177, 2017). "Recently, it was found that LAPTM4B can bind to EGFR, and subsequently enhance and prolong the EGFR signaling and initiate autophagy through a non-canonical EGFR signaling pathway and trafficking, which both facilitate the functions of EGFR on promoting cancer cell survival and proliferation." (PMID 27542271, 2016). "Phosphatidylcholine-specific phospholipase C interacts with HER2 and EGFR in HER2-overexpressing BC and EOC cells, while its pharmacologic inhibition may play a pivotal role in HER2 downmodulation, reduction of cell proliferation, and cancer cell differentiation." (PMID 27532027, 2016). "Constitutive activation of EGFR in cancer cells in the absence of extracellular ligands (under serum free conditions) is well known; however, it is not clear regarding whether this activation of EGFR is sustained by extracellular or intrinsic signals." (PMID 26378037, 2015).
cancer (continued). "Thus, NEU3 may be a potential target for cancer therapy as a molecule upstream of the EGFR/Src pathway, since the therapeutic efficacies of inhibitors for EGFR and Src have not been so encouraging despite many clinical trials for current anticancer therapies." (PMID 25803810, 2015). "However, activation of the EGFR in non-malignant cell populations of the neoplastic microenvironment might also play an important role in cancer progression." (PMID 26474280, 2015). "Furthermore, increasing evidences suggest that activation of EGFR in non-malignant cells of the neoplastic microenvironment might also play an important role in cancer progression and the pathogenesis of bone metastases." (PMID 26474280, 2015). "Despite this, response rates to EGFR inhibitors for LUSC studies are threefold higher than expected, suggesting that although EGFR itself may not be mutated, responders may still have a cancer which is dependent on EGFR signaling." (PMID 27047702, 2015). "In the absence of a Ras mutation, increased Ras activity in human cancer cells frequently results from gene amplification, gene overexpression, or an increase in activity of upstream signals from tyrosine kinase growth factor receptors such as Her2 and EGF receptor (EGFR)." (PMID 24662938, 2014). "We propose that response to combination endocrine/EGFRi therapies in ER+ luminal cancers may improve long-term survival in patients whose tumors have been preselected for presence of a luminobasal subpopulation based on ER/PR, CK5 and EGFR biomarker expression." (PMID 25116921, 2014). "Although the clinical significance of this pathway remains unclear, the EGF receptor (EGFR), a transmembrane glycoprotein belonging to the HER family of receptors, is recognized as a negative prognostic indicator and has shown clinical relevance as a molecular target of cancer therapies." (PMID 25153136, 2014). "Although the precise mechanism of LRIG1 downregulation in cancer cells remains unclear, the findings of a recent study demonstrated that LRIG1 forms a ternary complex between LRIG1, E-cadherin, and EGFR, which upon cell-to-cell contact negatively regulates EGFR signaling." (PMID 24709893, 2014). "Since TACC3 is overexpressed in cervical and other cancers and appears to be a key player in EGF/EGFR-driven EMT process, it is possible that depletion of TACC3 may be a good approach to treat cancers that are driven by EGF/EGFR signaling pathways or resistant to anti-EGFR therapy." (PMID 23936413, 2013). "In addition to the EGFR, the insulin-like growth factor-1 receptor (IGF1R) is a major regulator of Akt activation and cross-talk between IGF1R and EGFR or EGFR family members such as Her2 has been reported as a mechanism of resistance against drugs targeting EGFR or Her2 in several types of cancers." (PMID 22815959, 2012). "Recently it was published that the EGFR was not present on the surface of normal and cancer keratinocytes satisfying the criteria for stem cells, such as quiescence, sphere formation ability and expression of stem cell markers, while keratinocytes displaying EGFR had a more differentiated phenotype." (PMID 23049743, 2012). "Additionally, our findings demonstrate that the role of EGFR in HNSCC extends beyond its traditional function as a promoter of cell growth, as it could regulate the key properties of cancer stem cells that are essential for cancer initiation and progression." (PMID 22384257, 2012). "Thus, anti-Bcr Abl drugs (e.g. imatinib), anti-epidermal growth factor receptor drugs (e.g. Erbitux and Tarceva®), anti-ERB2 drugs (e.g. trastuzumab) or anti-VEGF receptor drugs (e.g. bevacizumab, semaxanib) have been developed and approved for a variety of cancer types." (PMID 22323550, 2012). "Thus, we hypothesized that EGFR+ CTCs might represent a potential negative biomarker of response to certain anti-cancer agents, including endocrine therapy in patients with HR+ BC." (PMID 22554015, 2012).
cancer (continued). "Furthermore, such mutations are uncommon in other cancers like HNSCC and may not be predictive of sensitivity to EGFR inhibitors in these cancers." (PMID 21908901, 2011). "Several receptor (EGFR, IGFR1, FGFR1...) and non-receptor (Abl) kinases have been selected, as well as serine/threonine/lipid kinases (AurA, Akt, CDKs, MAPKs...) implicated in main cancer pathways: cell cycle regulation, signal transduction, angiogenesis regulation among them." (PMID 21796074, 2011). "Interestingly, in the study by Voduc and colleagues which used IHC to determine subtype, those cancers that were triple-negative and negative for the expression of EGFR and CK5/6 (non-basal triple-negatives), had a lower incidence of locoregional relapse when compared to the basal-like subtype." (PMID 20979652, 2010). "In addition, we demonstrated that EGF show different functionality than NGF or GDNF and that EGF is a new potential analgesic modulator in the process of pain sensitization, a result of importance not least in the light of the increased use EGFR blockers for therapeutic cancer treatment." (PMID 21187008, 2010). "The interaction between EGFR and SGLT1 may represent a novel mechanism of adaptation by cancer cells to meet energy demand for cellular growth and suggests that EGFR contributes to increased cell survival and metastasis independent of the EGFR signalling pathway." (PMID 19888222, 2009). "This particular conjugate exhibited enhanced biological performance: it demonstrated selective uptake in EGFR-positive cancer cell lines (HT29 and HCT116), while minimal uptake was observed in EGFR-negative lines (HeLa and HEK293)." (PMID 40807472, 2025). "Expression analysis of brain metastasis-selective markers (BMSM), including HER2+/EGFR+/HPSE+/Notch1+, showed higher expression levels in CSCs compared to non-stem cancer cells." (PMID 41381440, 2025). "For example, cancer cells expressing specific oncogenes (MYC, RAS, AURKA, EGFR) generate higher numbers of EVs than their isogenic non-transformed counterparts, and these EVs markedly differ in their repertoires of proteins, lipids, RNA and DNA." (PMID 40563616, 2025). "Despite some genes lacking a direct link to EGFR, c-Met, or VEGF engagement, their biologic role in cancer development and response to TAVO412 treatment remains to be elucidated." (PMID 39995668, 2025). "Additionally, epidermal growth factor receptor–mutant adenocarcinomas may demonstrate only mild fluorodeoxyglucose uptake on positron emission tomography–CT, emphasizing that low metabolic activity does not exclude cancer." (PMID 41204513, 2025). "Integrins induce EGFR activation in the absence of EGF in normal epithelial cells and in cancer cells." (PMID 39594667, 2024). "In addition to EGFR-expressing cancer cells being targeted, bystander killing effects may contribute to ADC efficacy through the release of the membrane-permeable payloads from the internalizing cell following linker cleavage or by payload release following cancer cell death." (PMID 38772416, 2024). "Cancer cell lines M1, A549, SNU539, and H226 were tested with mAbs SB2, 3A4 (anti-CABYR, negative control), and AY13 (anti-EGFR, positive control)." (PMID 38485187, 2024). "We found that when EGFR-TKI is used together with another drug that blocks blood vessel growth (anti-VEGFR), they can delay the cancer from getting worse, but they do not necessarily make people live longer overall." (PMID 38539522, 2024). "The issue with using anti-cancer drugs such as gefitinib and erlotinib is the blood-brain barrier (BBB) permeability is not optimum for AD, but the EGFR inhibitors also showed neuroprotective potential in spinal cord injury." (PMID 38275516, 2024).
cancer (continued). "While the biochemical mechanism of AnxA6 inactivating phosphorylation of EGFR and ERK1/2 is not completely explored in cancer cells." (PMID 37528485, 2023). "As a cellular model, we used cancer cell lines known for their expression of EGFR and differential expression of ACE-2 including ACE-2 expressing lung (A549) and colon (HT-29) cancer cell and ACE-2 non-expressing Cervix (HeLa) adenocarcinoma cells." (PMID 37112680, 2023). "To determine specificity, we evaluated cancer cell lines expressing wildtype EGFR (MDA-MB-468, BT20 and A549), mutant EGFR (H1975) and non-transformed lines (CHO and MCF10A)." (PMID 36253541, 2023). "Next to the lack of discrimination between healthy and cancer cells, it has been reported that 111In-labelled EGF cannot discriminate between high and moderate EGFR overexpression." (PMID 37746282, 2023). "We also considered separately a fraction of 710 genes included in six major cancer-related molecular pathways (AKT, mTOR, EGFR, and Notch, WNT, and Hedgehog pathways) that form two non-overlapping regulatory axes." (PMID 37174700, 2023). "A recent example is EGFR to SCLC transformation following osimertinib therapy, which underscores the importance of non-genetic mechanisms at play in cancer resistance." (PMID 37445570, 2023). "Thus, our findings indicate a link among cisplatin resistance, EGFR hyperactivation, and TRPV1-mediated autophagic secretion, and implicate that TRPV1 could be a crucial drug target that could not only overcome cisplatin resistance but also alleviate pain in NANOG+ cisplatin-resistant cancer." (PMID 37165076, 2023). "Despite achieving encouraging progress in various cancers, these treatments have not achieved the expected effectiveness in GBM patients with EGFR alterations." (PMID 37601668, 2023). "EGFR-mut and KRAS-mut cancers, but not NEK cancers, had both stabilizing and directional selection among genes of the membrane protease family TMPRSS." (PMID 36612014, 2022). "It is also important to note that PEPDG278D induces the degradation of EGFR and HER2 when they are overexpressed as in cancer cells but not when they are expressed low as in normal cells." (PMID 35650607, 2022). "Although the mechanisms by which BCAR4 can activate EGFR have not been fully elucidated, the contribution of BCAR4 to cancer progression makes this plausible." (PMID 36081848, 2022). "LUAD1 enriched for alterations in EGFR, MN1 and MYH9, LUAD2 enriched for BRCA2, while LUAD3 did not enrich for known cancer drivers." (PMID 35383171, 2022). "Therefore, targeting EGFR may not be the best course of therapy for certain cancer types including HPV-positive HNSCC, while targeting specific signalling pathways such as BRD4 could provide a better and potentially new treatment to improve HNSCC therapeutic outcome." (PMID 36333293, 2022).
cancer (continued). "Similarly, therapy responses can be different among these two kinds of colorectal tumors: cancer patients with left-sided tumors may be responsive to anti-EGFR targeted therapy, while those with right-sided tumors do not have the same benefit from conventional treatments." (PMID 36011003, 2022). "The Kd values of MEK5, which showed high affinity in %Ctrl, and EGFR, FGFR1, and FGFR2, which were further analyzed (highly correlated with cancer proliferation and metastasis), were not significant." (PMID 35454900, 2022). "A single cut in the normal diploid chromosomal EGFR locus did not result in a DNA band (as shown in Jurkat cells), further supporting enrichment of ecDNAs in GBM39 cancer cells." (PMID 36253572, 2022). "To clarify the effect of metformin on the expression of EGFR in patients with T2DM and OSCC, we conducted a study on EGFR in cancer tissues of non-diabetic OSCC patients taking metformin." (PMID 35222283, 2022). "In contrast to EGFR, SLC35B2 has not been investigated in the context of cancer and drug resistance." (PMID 35798875, 2022). "EPCAM, EGFR, and MUC1 glycoproteins are overexpressed only on the surface of epithelial cancer cells, not on cancer cells with mesodermal and ectodermal origins." (PMID 34679012, 2021). "Future scrutiny will also involve CPI combination with TKI in never smoking molecular subsets beyond EGFR and ALK positive cancers, including those with BRAF V600, RET fusion and MET exon 14 who have shown promising TKI efficacy." (PMID 32915318, 2021). "The EGFR has been demonstrated to show a negative correlation with DEPTOR and activated mTOR phosphorylation in human cancers." (PMID 34540820, 2021). "Although the EGF-activated PI3K/Akt/CREB signaling axis upregulates SGLT1 expression and enhances glucose uptake in intestine epithelial cells, the tyrosine kinase activity of EGFR or IGF1R and Akt signals are not needed for SGLT1 upregulation in cancer cells." (PMID 34155348, 2021). "Approximately three-quarters of patients in both studies had stage 1 cancer, and recurrence patterns, including timing and sites of recurrence, among those with EGFR-positive NSCLC relative to those with wildtype EGFR have not been well characterized." (PMID 34739062, 2021). "Furthermore, these synthesized compounds can inhibit epidermal growth factor receptor (EGFR) (IC50: 0.24 μM), proto-oncogene tyrosine-protein kinase (Src) (IC50: 0.96 μM), and interleukin-6 (IL-6) (% of control: 20%) and might play anticancer roles in various cancers." (PMID 34208562, 2021). "Although not investigated in cancer, heterodimerization within other RTK families, particularly EGFR, is known to mediate critical signaling in tumorigenesis." (PMID 34068954, 2021). "Even though drugs targeting tyrosine kinase activity (e.g., HER2, FGFR, EGFR, VEGFR2), can prolong survival by inducing cancer regression, the lack of selectivity to a single target and/or development of drug resistance remains a problem." (PMID 34830836, 2021). "While the KYSE-30 and CAL-27 showed a strong and specific extracellular membrane positivity for anti-EGFR antibody, there was no such reactivity measured in the Hep G2 and MCF-7 cancer cell lines." (PMID 34683944, 2021). "Anti-EGFR therapy including cetuximab and panitumumab significantly improves the survival of KRAS wild-type MSKCC, but not of those with KRAS-mutant cancer, suggesting that the single-drug therapy of cetuximab is insufficient to achieve a therapeutic effect." (PMID 34299137, 2021). "KIR2DL2/L3/S2+ CD8+ T lymphocytes exhibited over-expression of genes that are not usually expressed in CD8+ T cells, i.e., EGFR, ITGB1, MAP2K1, and CD86, indicating that these cells are reprogrammed to the AKT/PI3K cancer pathway." (PMID 33076479, 2020).